HGF (hepatocyte growth factor)
Diseases named in the same sentence as HGF in open-access papers (continued):
Sharing a sentence is not in itself a finding about the gene and the disease.
tumor (continued). "Furthermore, mutations, overexpression, or amplification of the MET gene in some tumor types resulted in aberrant HGF/c-Met axis activity, which induced cell motility and proliferation, promoted tumor development, and led to resistance to radiotherapy and targeted drug therapy in multiple cancers." (PMID 32219093, 2020). "However, several studies have suggested that HGF could also have a pro-immune role and further research is needed to better understand the exact role of HGF in anti-tumour immune response." (PMID 33396187, 2020). "Furthermore, HGF plays a role in metabolic reprogramming of tumor cells." (PMID 31940827, 2020). "The increased expression of hepatocyte growth factor (HGF) and its physiological receptor tyrosine kinase MET have been shown to be linked to acquired resistance to various tyrosine kinase inhibitors (TKIs), and this phenomenon has been observed in some ALK-positive NSCLC tumour tissues." (PMID 32041944, 2020). "Thus, the hypothesis that systemic infection is involved in the tumor growth via the HGF/c-Met signaling pathway may be reasonable." (PMID 32630328, 2020). "HGF is not secreted by the tumor cells itself, but by tumor-associated fibroblasts." (PMID 31940827, 2020). "Moreover, studies also illustrated that deregulated c-Met is associated with the invasiveness and progression of HCC and anti-tumor mechanisms of many components extracted from Chinese herbal medicine and plants were related to the expression level of HGF/c-Met." (PMID 32117722, 2020). "Similarly, the tumor-promoting functions of CAF-derived HGF were also observed in gastric cancer." (PMID 31106200, 2019). "Thus, the biological significance of the HGF/ c-Met pathway in the development, progression and metastasis of kidney cancer was confirmed by the demonstration of the correlation between c-Met expression and tumor progression." (PMID 30909397, 2019). "HGF is a growth factor for various cells such as hepatocytes and epithelial cells with evidence demonstrating that HGF plays an important role in growth stimulation, migration, morphogenesis, angiogenesis, tissue regeneration, tumorigenesis, and tumor invasion." (PMID 31915446, 2019). "Notably, overexpression of Smad7 in Ikkβ-deficient fibroblasts prevented HGF secretion thus confirming the tumor-suppressor role of Smad7 expressed by non-epithelial cells." (PMID 31052449, 2019). "Indeed, the HGF/c-MET system plays an essential role in tumor–stromal crosstalk." (PMID 30352967, 2018). "Interestingly, HGF induces release of NO by neutrophils in a autocrine fashion to kill cancer cells, suggesting a negative feedback loop involved in interplays between neutrophils and transformed cells during tumor progression." (PMID 30473691, 2018). "ROS generation may be induced intracellularly in either a NADPH oxidase-dependent manner or a mitochondria-dependent manner, by growth factors and cytokines (such as TGF beta and HGF) or by tumor promoters (such as TPA) capable of triggering cell adhesion, MET, and migration." (PMID 29062841, 2017). "Thus, MP0250 was tested in the VEGF-A dependent A673 model and the HGF-dependent U87MG tumor model." (PMID 29228696, 2017). "Also, control of tumor metabolism by HGF may bring new life to the many HGF/MET inhibitors that are currently struggling to find an application in oncology." (PMID 28445144, 2017). "Likewise, increased c-Myc alters the expression of secreted factors in HCC cells which can lead to changes in the tumor microenvironment that facilitate tumor progression, including the induction of angiogenesis and the activation of pro-fibrotic and HGF-secreting hepatic stellate cells." (PMID 29254183, 2017). "Within tumor microenvironment, the primary tumors may activate stromal and inflammatory cells leading to the secretion of a lot of metastatic factors including hepatocyte growth factor (HGF), epidermal growth factor (EGF), and transforming growth factor-β (TGFβ)." (PMID 26840563, 2016).
tumor (continued). "Thus, it was of interest to evaluate the impact of partial hepatectomy on tumor growth as well as to evaluate the correlation between H19 and HGF levels in tumors and in the liver after hepatectomy in the animal models being used to evaluated BC-819 therapy of liver metastases." (PMID 26623562, 2016). "Our studies confirmed that HCC cell-derived exosomes induced sorafenib resistance by increasing HGF levels in the tumor microenvironment and activating the c-Met/Akt pathway in vitro, suggesting that HGF/c-Met may be an important target for improving sorafenib resistance of HCC." (PMID 27716356, 2016). "Studies have suggested that HGF/c-Met can stimulate the expression of vascular endothelial growth factor, which can promote endothelial cell division and increase vascular permeability to stimulate angiogenesis while altering tumor matrix and promoting tumor growth and metastasis." (PMID 27069297, 2016). "Activation of c-Met signaling and/or HGF up-regulation in the tumor microenvironment may confer resistance to RTKs-targeting cancer therapies already in clinical use, including epidermal growth factor receptor (EGFR) and v-RAF murine sarcoma viral oncogene homolog B1 (BRAF) kinase inhibitors." (PMID 27086914, 2016). "However, because the transforming potential of mutant MET appears to depend on the presence of HGF, it is possible that inhibitors of HGF activation may block tumor progression in cancers that are driven by mutant MET." (PMID 27121052, 2016). "Additionally, the platelet-derived growth factor, basic fibroblast growth factor and hepatocyte growth factor could enhance tumor cells’ capability to metastasis." (PMID 27739490, 2016). "Tumor-derived secreted factors such as TGF-β1, bFGF, and IL-6, have been shown to control the activation of cancer associated fibroblasts (CAFs), and the proteome/secretome of these CAFs, including hepatocyte growth factor (HGF), has been found to enhance the invasiveness of cancer cells." (PMID 27793046, 2016). "Overall, results obtained in MCF-7 cells suggest that HGF might be the major factor involved in the CAF-induced promotion of tumor cell migration speed, whereas for the highly invasive MDA-MB-231 cells the three growth factors seem to almost equally contribute." (PMID 25880005, 2015). "Hence, the observed reductions of TGFβ, FGF2, IL-6 and HGF can not only be due to the reduction of tumor-infiltrating CAFs but also due to quantitative and/or qualitative changes in other intratumoral cell populations such as reduced numbers of ECs due to an anti-angiogenic effect of the treatments." (PMID 25849942, 2015). "Neoadjuvant therapy may influence HGF serum levels in a different way than in the tumor tissue." (PMID 25885021, 2015). "We further investigated whether Hic-5 can be induced in the low Hic-5 expressing HCCs such as HCC340, H363 and HCC374 by metastatic factors such as HGF and the tumor promoter 12-O-tetradecanoyl-phorbol-13-acetate (TPA), known to be a potent inducer of HCC migration." (PMID 26416447, 2015). "Furthermore, various studies of pancreatic- and colorectal-derived exosomes have indicated a transfer of growth factor encoding mRNA (VEGF, HGF, IL-8, CD44H) to tumor-associated monocytes, leading to an anti-apoptotic response due to the activation of the Akt pathway." (PMID 25644060, 2015). "The tumor growth promotion is supported by the fully glycanated endocan through two main mechanisms requiring the presence of a glycan chain: a comitogenic property with several growth factors like FGF-2 or HGF/SF, and a chemokinetic property on endothelial cells." (PMID 25575808, 2015). "In conclusion, the results of the present study revealed that elevated pre-operative serum HGF levels were indicative of invasive growth of tumor foci, categorized as IFNγ, and characterized by high-grade tumors with an unclear border between the tumor and the surrounding tissue." (PMID 25592281, 2015).
tumor (continued). "We think that delivery of human HGF mRNA into human tumor cells may be one of mechanisms of action." (PMID 24797571, 2014). "PDGF, HGF, and other growth factors could induce the migration of MSCs to tumor cells." (PMID 24502410, 2014). "Thus, the enhanced waves of directionality and coordination found here might imply that even in tumor cells, HGF/SF-Met activate similar pathways to those activated during embryogenesis." (PMID 25058592, 2014). "In addition, the minor alleles of three HGF variants associated with the clinical variables of higher tumor grade, positive nodal status, bigger tumor size, negative ER and PR status, and overall higher tumor stage." (PMID 25029565, 2014). "However, it is possible that a cross-talk between HMGB1/TNF-α and HGF/Met/Akt may occur in MM also, supporting and reinforcing the process of MM carcinogenesis and tumor progression." (PMID 28548074, 2014). "In our opinion, delivery of HGF mRNA into tumor cells may be one of inductive mechanisms." (PMID 24797571, 2014). "The fact that the majority of patients had a decrease of sHGF levels at response evaluation (where the majority of patients do actually respond to treatment) supports the hypothesis of HGF being secreted, at least in part, by tumor cells in an autocrine manner, as described in other tumor models." (PMID 25026301, 2014). "Reagents to evaluate intratumoral levels of HGF protein have not been vigorously validated with respect to sensitivity and specificity and it remains unclear how systemic levels of HGF in the serum/plasma relate to HGF levels and pathway activity in the tumor microenvironment." (PMID 24930887, 2014). "However, HGF derived from the tumor microenvironment has recently been shown to protect MET-amplified cells, otherwise sensitive to MET inhibitors, suggesting a role for the ligand in the resistance to anti-MET therapy, and providing the basis for the use of HGF-neutralizing drugs." (PMID 28548076, 2014). "Thus, proteolytic activation of pro-HGF is an essential step in tumor progression, while the inhibition of pro-HGF activation could be an alternative target for controlling tumor metastasis." (PMID 23296269, 2013). "Cells (tumor associated macrophages (TAM), myeloid derived suppressor cells (MDSC), tumor associated dendritic cells, mesenchymal stromal cells and tumor cell itself) within TME produce several angiogenic growth factors, like, VEGF, PDGF, TGFβ and HGF that stimulate tumor cell proliferation." (PMID 23785504, 2013). "Furthermore, tumor cells could up-regulate HGF production, through paracrine and/or autocrine mechanisms, by the surrounding stromal cells or cancer cells themselves." (PMID 23379953, 2013). "Despite multiple checkpoints, HGF-cMET axis dysregulation occurs in a variety of solid tumors and hematopoietic derived malignancies and plays a key role in malignant transformation by promoting tumor cell migration, epithelial to mesenchymal transition, invasion, proliferation, and angiogenesis." (PMID 23606971, 2013). "HGF/SF is another pro-metastatic factor that may be upregulated by chemo/radiotherapy, which after binding to tyrosine kinase receptor c-Met activates mitogenic pathways and thus plays an important role in tumor growth." (PMID 24373588, 2013). "This study strongly suggests that HGF antagonism may break immune tolerance in tumor-bearing hosts." (PMID 23232072, 2012). "Therefore, inhibitors targeting HGF/c-Met signaling may be an effective therapeutic approach to control angiogenesis and prevent tumor growth." (PMID 21876694, 2012). "NK4 may exert antiangiogenic and tumor-suppressing activities independently of HGF antagonism." (PMID 22567028, 2012). "Furthermore, PAK1 knockdown substantially decreased tumor cell proliferation (imaged by immunofluorescence staining of Ki-67 positive nuclei), migration and actin dynamics induced by hepatocyte growth factor (HGF) treatment." (PMID 21653999, 2011).
tumor (continued). "Thus, PHA665752 could potentially inhibit HGF-stimulated tumor proliferation/migration resulting from either paracrine (i.e. tumor microenvironment) or autocrine exposure to HGF." (PMID 19939254, 2009). "Furthermore, HGF is among the most aberrant cytokines present in tumours." (PMID 17576468, 2007). "The discovery of transcription activation of HGF in epithelial-originated cancer cells, thought to occur through the cSrc and Stat3 pathways 7, comes in addition to the knowledge that stromal cells in tumour tissues overexpress the HGF transcript and HGF protein." (PMID 17576468, 2007). "LINC00240 and miR-101 modulate this pathway through HGF/c-MET or its downstream effectors, which affect tumour cell viability and invasion." (PMID 41476776, 2026). "In this model, SDF-1 and HGF promote the recruitment and activation of stromal cells, while LIF and, possibly, SCGF-β directly target tumor cells by activating key oncogenic signaling pathways such as JAK/STAT3 and PI3K/Akt." (PMID 41597220, 2026). "Downstream effectors of HGF/c-MET signalling regulate proliferation, survival and metastasis and hence facilitate tumour progression." (PMID 41476776, 2026). "HGF/cMET pathway activates cytoskeletal reorganization and invasion; PI3K/AKT/mTOR is involved in tumour cell survival and chemoresistance." (PMID 41476776, 2026). "Mechanistically, ZFAS1 functions as a competitive endogenous RNA (ceRNA) that sequesters tumor-suppressive miRNAs including miR-150 and miR-193a-3p, thereby de-repressing downstream oncogenic targets such as ZEB1/MMP14 and RALY/HGF/c-Met." (PMID 41450817, 2026). "Its ability to induce potent cytotoxicity in cancer cell lines, particularly MDA-MB-231 and T98G, while minimizing damage to hGF and ARPE-19 cells, suggests the presence of compounds with tumor-preferential activity." (PMID 41304951, 2025). "Another pro-tumorigenic growth factor produced by CAFs is the hepatocyte growth factor (HGF), which binds to c-MET on tumor cells and activates the downstream MAPK, extracellular signal-related kinase (ERK), and PI3K pathways." (PMID 39858054, 2025). "Platelet-derived extracellular vesicles enhance tumor proliferation via the MAPK signaling pathway and promote angiogenesis by stimulating angiogenic factors, such as MMP-9, IL-8 and hepatocyte growth factor (HGF)." (PMID 41429896, 2025). "NK4 inhibits the paracrine loop of HGF, indirectly suppressing the expression of VEGF in tumor cells, thereby exerting an anti-angiogenic effect." (PMID 40823073, 2025). "In these sites, neutrophils release growth factors like hepatocyte growth factor (HGF) and colony-stimulating factor (CSF), which promote tumor cell survival and proliferation." (PMID 40227814, 2025). "When activated via binding to its ligand hepatocyte growth factor (HGF), the HGF/c-MET signaling pathway plays a critical role in tissue regeneration and tumor mitogenesis, motility, invasiveness, morphogenesis, and angiogenesis." (PMID 39968425, 2025). "Once activated, CAFs release growth factors, including fibroblast growth factor (FGFs), hepatocyte growth factor (HGF), and insulin-like growth factor (IGF) that promote tumour cell proliferation, motility, and invasion." (PMID 41463236, 2025). "They promote tumor growth through paracrine signaling (e.g., TGF-β, FGF, EGF, HGF), activate proliferative pathways (MAPK, PI3K/AKT), and remodel the extracellular matrix to support expansion." (PMID 40732242, 2025). "Conversely, basic fibroblast growth factor (bFGF) produced by tumor cells stimulates MAPK signaling in CAFs, enhancing both their proliferation and subsequent HGF secretion." (PMID 41583435, 2025). "By secreting a variety of Cytokines, such as TGF-β and HGF, along with growth factors like VEGF, significant influences are exerted on the biological behavior of Tumor Cells." (PMID 41333481, 2025). "Targeting the HGF/c-Met axis, along with MACC1, offers a promising strategy for inhibiting tumor progression." (PMID 40354443, 2025).
tumor (continued). "Furthermore, TFPI2 may promote M2-type tumor-associated macrophages (TAMs) via PPARγ, which support tumor growth through immune evasion, angiogenesis, and ECM remodeling by releasing factors like epidermal growth factor (EGF), hepatocyte growth factor (HGF), VEGF, MMPs, IL-10, and TGF-β." (PMID 40361374, 2025). "Angiogenesis facilitates tumor growth by supplying nutrients and oxygen through new blood vessels, with cytokines such as VEGF, HGF, basic-FGF, and PDGF-BB being key mediators." (PMID 41048959, 2025). "As murine HGF cannot activate the human MET receptor, we used this humanised mouse model expressing human HGF to assess tumour progression using PC3M cells." (PMID 39374163, 2025). "Cancer‐associated fibroblasts (CAFs) secrete growth factors such as HGF, IGF‐1, FGF and TGF‐β, activating pathways like PI3K/Akt/mTOR and MAPK, which promote tumour proliferation, increase macromolecule synthesis, and lead to cell volume expansion." (PMID 40525649, 2025). "HGF produced by CAFs can activate the c-MET receptor tyrosine kinase on tumour cells, promoting tumour growth and metastasis." (PMID 39780187, 2025). "In PDAC, elevated AHNAK2 levels promote tumor progression by preventing c-MET degradation, thereby sustaining HGF/c-MET pathway activation." (PMID 40308776, 2025). "Initially, it was believed that TANs primarily functioned as tumor promoters in CRC, contributing to tumor invasion and angiogenesis through the production of MMP9, VEGF, and hepatocyte growth factor (HGF)." (PMID 40255905, 2025). "After liver colonization, influenced by environmental factors such as hepatocyte growth factor (HGF) and fibroblast growth factor (FGF), metastatic tumor cells re‐express Lgr5 to support their growth in the liver." (PMID 40027151, 2025). "Based on the transcriptomics data, we generated the spatial expression mapping of HGF (stroma-enriched), MET, and MYC (tumor-enriched), and confirmed their co-localization within High-M CRC regions bordering mCAFs." (PMID 41234356, 2025). "MET, a receptor tyrosine kinase (RTK), is activated by ligands such as hepatocyte growth factor (HGF)/scattering factor (SF) and drives key processes in tumor progression, including invasion, proliferation, and angiogenesis." (PMID 40673866, 2025). "MAbs targeting the MET receptor primarily function by competitively inhibiting the binding of HGF to MET, effectively suppressing downstream signaling and reducing tumour cell proliferation and migration." (PMID 40599602, 2025). "Spatial transcriptomic validation confirmed this spatially structured interaction, with co-localization of mCAFs, HGF, MET, and MYC targets within specific tumor regions." (PMID 41234356, 2025). "Fibroblasts and mesenchymal stromal cells in the tumor stroma secrete cytokines such as HGF and FGF to promote angiogenesis, whereas stromal-related factors such as ISF-1 and IGF-2 promote tumor cell infiltration." (PMID 41281744, 2025). "Hepatocyte growth factor, one of the essential growth factors in the HCC microenvironment, represses tumor suppressor genes via DNMT1‐mediated DNA hypermethylation." (PMID 40761482, 2025). "CAFs also secrete growth factors such as TGF-β, fibroblast growth factor (FGF), epidermal growth factor (EGF), and hepatocyte growth factor (HGF) to induce EMT-like CAMs and exacerbate the aggressiveness and resistance of tumor cells." (PMID 40510029, 2025). "The HGF/c-MET signaling pathway plays a pivotal role in tumorigenesis and disease progression, promoting malignant tumor development through diverse mechanisms, including cell proliferation and migration." (PMID 41233563, 2025). "Additionally, the dynamic changes in HGF expression are closely linked to the composition and activation states of immune cells within the LUAD tumor microenvironment, potentially exerting a critical influence on immune evasion mechanisms and tumor response to therapy." (PMID 40136462, 2025).